RGS9 (regulator of G protein signaling 9)
Description:
Inhibits signal transduction by increasing the GTPase activity of G protein alpha subunits thereby driving them into their inactive GDP-bound form. Binds to GNAT1. Involved in phototransduction; key element in the recovery phase of visual transduction (By similarity).
Synonyms: PERRS; RGS9L; MGC26458; MGC111763; PERRS1
Tractability: Antibody: its Gene Ontology location is reachable by antibodies, with high confidence; UniProt places it where antibodies can reach, with medium confidence. PROTAC: ubiquitination databases record sites on it.
Gene: Protein-coding gene on chromosome 17 (65,100,812 to 65,227,703, forward strand). Ensembl gene ENSG00000108370.
Subcellular location: Membrane (Isoform 3)
Subcellular location (Human Protein Atlas): Nucleoplasm; Vesicles
Pathways (Reactome):
Metabolism of proteins: Cooperation of PDCL (PhLP1) and TRiC/CCT in G-protein beta folding
Sensory Perception: Inactivation, recovery and regulation of the phototransduction cascade
Signal Transduction: G alpha (i) signalling events
Gene Ontology:
Molecular function: protein binding; GTPase activator activity; GTPase activity
Biological process: G protein-coupled dopamine receptor signaling pathway; G protein-coupled receptor signaling pathway; regulation of G protein-coupled receptor signaling pathway; intracellular signal transduction; nervous system development; regulation of calcium ion export across plasma membrane; response to amphetamine; response to estradiol
Cellular component: cytoplasm; neuron projection; plasma membrane; glutamatergic synapse; membrane; postsynaptic density membrane; presynaptic membrane
Genetic constraint (gnomAD): Loss-of-function variants: 58 observed, 82.41 expected, observed/expected ratio (o/e) 0.7, 90% interval 0.57 to 0.88. The upper end of that interval is the gene's LOEUF score, 0.88, which puts it in group 3 of 6, group 1 being the genes least tolerant of losing a copy. Missense variants: 759 observed, 815.5 expected, observed/expected ratio (o/e) 0.93, 90% interval 0.88 to 0.99. Synonymous variants: 331 observed, 309.5 expected, observed/expected ratio (o/e) 1.07, 90% interval 0.98 to 1.17.
Gene-disease validity (ClinGen):
ClinGen rates the evidence that RGS9 causes each of these diseases.
bradyopsia (autosomal recessive): Moderate. Bradyopsia is characterized by prolonged electroretinal response suppression leading to difficulties adjusting to changes in luminance, normal to subnormal acuity and photophobia.
Homologues: Orthologues: chimpanzee RGS9 (99% identical), macaque RGS9 (96% identical), guinea pig RGS9 (91% identical), rat Rgs9 (91% identical), mouse Rgs9 (91% identical), rabbit RGS9 (91% identical), dog RGS9 (90% identical), pig RGS9 (89% identical), zebrafish rgs9b (54% identical), zebrafish rgs9a (41% identical). Paralogues in human: RGS11 (35% identical), RGS6 (27% identical), RGS7 (27% identical), RGS12 (17% identical), RGS22 (16% identical), RGSL1 (15% identical), AXIN1 (14% identical), RGS3 (14% identical), AXIN2 (13% identical), RGS14 (12% identical), RGS1 (10% identical), RGS5 (10% identical), and 11 more.
Diseases named in the same sentence as RGS9 in open-access papers:
RGS9 is named in the same sentence as 37 diseases in open-access papers, as found by Europe PMC text mining. Sharing a sentence is not in itself a finding about the gene and the disease. The quoted sentences say what the papers report.
bradyopsia (5 papers, 2011 to 2025). "By elucidating how genetic mutations such as RGS9 (bradyopsia) and AIPL1 (LCA) affect vision, the CCT aids in precise diagnoses and the discovery of novel genetic causes of color vision disorders, potentially guiding the development of new therapies." (PMID 40364109, 2025). "Bradyopsia is caused by genetic defects in RGS9 or R9AP, which are associated with defects in RGS9 or its anchor protein R9AP." (PMID 37959417, 2023). "Bradyopsia (RGS9/R9AP-associated retinopathy) is characterized by reduced central vision from childhood, with mild photophobia, absence of nystagmus, normal color vision and night vision, and normal fundus appearance." (PMID 26343007, 2015). "Finally, bradyopsia, a condition characterized by delayed cone response, mimics ACHM but results from a pathogenic variant in the RGS9 gene, which plays a key role in the phototransduction cascade." (PMID 40364109, 2025).
Dyskinesia (3 papers, 2011 to 2017). A movement disorder which consists of effects including diminished voluntary movements and the presence of involuntary movements. "RGS9-deficient mice show drug-induced dyskinesia but normal locomotor activity under unchallenged conditions." (PMID 24663062, 2014). "Indeed, RGS9–2 plays a role in the occurrence of motor anomalies in LID, since RGS9–2 KO mice develop dyskinesia associated with D2R dysfunctions, and RGS9–2 overexpression diminishes L-DOPA-induced involuntary movements." (PMID 28228718, 2017). "RGS9-deficient mice represent a genetic animal model for the phenotype of drug-induced dyskinesia." (PMID 24663062, 2014). "In summary, RGS9-deficient mice show significant changes in striatal function including enhanced DARPP32 and ERK phosphorylation that are characteristically found in L-DOPA-induced dyskinesia." (PMID 24663062, 2014). "In addition, RGS9 knockout mice show accelerated development of drug-induced dyskinesia, while HSV-mediated overexpression of RGS9-2 in the striatum of rats and monkeys diminished intensity of drug-induced dyskinesia." (PMID 22132185, 2011). "However, in RGS9-deficient mice that are treated with the D2R-specific agonist quinpirole following pretreatment with reserpine exhibit pronounced dyskinesia that is absent in wild-type (wt) mice." (PMID 24663062, 2014). "Consistently, overexpression of RGS9 in dyskinetic non-human primates resulted in a reduction of such L-DOPA-induced dyskinesia." (PMID 24663062, 2014).
schizophrenia (3 papers, 2011 to 2021). A major psychotic disorder characterized by abnormalities in the perception or expression of reality. "Therefore, we investigated the association between the RGS9 gene and two related dopamine psychoses, schizophrenia and methamphetamine use disorders." (PMID 21886588, 2011). "Accordingly, in a rat model of schizophrenia with sensitization to amphetamine and in patients suffering from schizophrenia, reduced levels of RGS9 were detected." (PMID 24663062, 2014). "In conclusion, this study showed that the RGS9 gene is unlikely play a major role in schizophrenia and methamphetamine use disorder liability and/or the development of methamphetamine induced psychosis, at least in a Japanese population." (PMID 21886588, 2011). "Schizophrenia patients often show a supersensitivity of D2R and/or an increase in DA, and mice in a corresponding mouse model show the decrease in the gross expression level of RGS9–2 in the striatum." (PMID 34591840, 2021). "Therefore, it is possible that the haplotype consisting of these markers is associated with functional changes in RGS9, and a possible candidate for RGS9 analyses for methamphetamine use disorder or schizophrenia." (PMID 21886588, 2011). "The present study suggested that the RGS9 gene is unlikely to play a major role in schizophrenia and methamphetamine dependence liability and/or the development of methamphetamine induced psychosis, at least in a Japanese population." (PMID 21886588, 2011). "In schizophrenia, the balance between D2R and RGS activities is considered to be biased toward D2R, because D2R blockers works as antipsychotic drugs for schizophrenia, and schizophrenia shows show a supersensitivity of D2R and/or an increase in striatal DA as well as a decrease in striatal RGS9–2." (PMID 34591840, 2021).
ischaemic stroke (2 papers, 2015 to 2021). "Previously, we identified the human orthologues for a number of rat genes, which expression was changed after ischaemic stroke (Adora2a, Bcl3, Ccl22, Ccr1, Cd14, Gpr6, Gpr88, Rgs9, and other genes)." (PMID 34946819, 2021). "Among the downregulated genes, Gpr88, Rgs9, Enthd1, Olr59, P2ry12, Degs2, Pde10a, Neu2, Adora2a, and Slc22a6 were found to demonstrate significant downregulation in pathological phase of ischemic stroke." (PMID 25861363, 2015).
Obesity (2 papers, 2020 to 2024). Accumulation of substantial excess body fat. "A trend of increased RGS9 expression was demonstrated in both all-EECs and L-type EECs in obesity compared to lean (Log2FC = 0.29, p = 0.19, Log2FC = 0.61, p = 0.10, respectively)." (PMID 39142076, 2024). "Protein expression of colonic RGS9 was additionally confirmed to be overexpressed in obesity (n = 10), compared to lean (n = 9) (1.23 ± 0.28 vs. 0.99 ± 0.11, respectively, mean difference 0.24 [95% CI 0.035–0.45], Log2FC = 0.30, p = 0.026)." (PMID 39142076, 2024). "Overexpression of whole colonic RGS9 in obesity was further validated in whole human colonic mucosa and additionally associated with BMI." (PMID 39142076, 2024). "Here, we show in colonic EECs, obesity was associated with an altered RGS profile, with differential expression patterns in colonic RGS2 (underexpression), RGS4 (underexpression), RGS9 (overexpression), and RGS12 (overexpression)." (PMID 39142076, 2024). "Colonic RGS9 demonstrated significant overexpression in obesity compared to lean (0.0033 ± 3.9e-004 vs. 0.0012 ± 2.1e-004, respectively; mean difference 0.002142 [95% CI 0.001250–0.003035], Log2FC = 1.50; p < 0.0001)." (PMID 39142076, 2024). "However, In our cohorts fasting and postprandial GLP-1 and PYY were not altered in obesity; therefore, it is unlikely overexpression of RGS9 represents a universal pathophysiological process in obesity." (PMID 39142076, 2024). "The RGS family, specifically RGS9, may serve as novel targets for the modulation of satiety hormone secretion in obesity." (PMID 39142076, 2024). "While the single-cell data set identified RGS2, RGS4, RGS9, and RGS12 as having physiologically relevant transcriptional alterations within EECs in obesity, this finding was only validated for RGS9 in the colon." (PMID 39142076, 2024). "Using this criteria RGS2, RGS4, RGS9, and RGS12 were identified as having physiologically relevant transcriptional alterations in obesity compared to lean." (PMID 39142076, 2024). "In EECs, RGS, specifically RGS9, may modulate the secretion of nutrient-stimulated GPCR-mediated GLP-1 and PYY from gut L cells, and this system may serve as a potential target for the pharmacological treatment of obesity." (PMID 39142076, 2024).
prostate tumor (2 papers, 2016 to 2020). "However, MIC(X1; X2; Y) suggests that LINC01278, RGS9 and DIAPH2 are important informative genes for prostate tumors, and should be given proper attention." (PMID 27470995, 2016).
Ataxia (1 paper, 2015). Ataxia refers to impaired coordination of voluntary muscle movement. "Mice lacking Rgs6 or Rgs9 exhibit motor function deficits and ataxia." (PMID 25902068, 2015).
congenital stationary night blindness (1 paper, 2024). "Mutations in RGS9, which terminates light signaling by accelerating the activity of the G protein GTPase, lead to abnormalities in light signaling, which in turn cause retinitis pigmentosa and congenital stationary night blindness." (PMID 39728691, 2024).
coronary artery disease (1 paper, 2017). "Six genes (ABCB1, PLAT, ACE, GH1, PECAM1, and RGS9) known to predispose people to coronary artery disease occur in the cn-LOH regions identified." (PMID 28120895, 2017).
depression (1 paper, 2021). "Thus, loss of Rgs7, but not Rgs9, in the striatum selectively affects depression-related behaviors." (PMID 33402347, 2021).
Dystonia (1 paper, 2021). An abnormally increased muscular tone that causes fixed abnormal postures. "In DYT1 dystonia, a movement disorder, the balance between D2R and RGS9–2 is conversely biased toward RGS9–2." (PMID 34591840, 2021). "However, because DYT1 dystonia alters protein trafficking, the expression level of RGS9–2 is selectively increased in the fraction of DRM where D2Rs is located, and the perpendicular change appeared in the space of D2R and RGS9–2 (red points)." (PMID 34591840, 2021).
oligocone trichromacy (1 paper, 2015). Oligocone trichromacy is a rare non-progressive form of cone photoreceptor dysfunction characterized by reduced visual acuity, normal retinal appearance, absent or reduced cone responses on electroretinography but normal color vision. "While patients with either RGS9/R9AP-associated retinopathy or oligocone trichromacy have very similar clinical phenotypes, we highlight the utility of cellular imaging in both effectively distinguishing between these conditions and determining the potential for therapeutic intervention." (PMID 26343007, 2015).
retinal degeneration (1 paper, 2014). Degeneration of the retina. "In Mfrprd6 eyes, a significant 1.5- to 2.0-fold decrease was observed among transcripts of genes linked to retinal degeneration, including those involved in visual cycle (Rpe65, Lrat, Rgr), phototransduction (Pde6a, Guca1b, Rgs9), and photoreceptor disc morphogenesis (Rpgrip1 and Fscn2)." (PMID 25357075, 2014).
thyroid cancer (1 paper, 2020). "We detect a number of recurrent fusions, such as those involving ANO3, RGS9, FUT5, CHI3L1, OR1D4, and LIPG in breast; IGF2 in colon; ETV1 in prostate; and IGF2BP3 and SIX2 in thyroid cancers." (PMID 32631391, 2020).
retinopathy (4 papers, 2015 to 2021). "Oligocone trichromacy and RGS9/R9AP-associated retinopathy share clinical characteristics including stationary cone dysfunction, mild photophobia, normal color vision, and normal fundi." (PMID 26343007, 2015). "In this study, we have undertaken deep phenotyping of molecularly proven patients with either RGS9- or R9AP-associated retinopathy." (PMID 26343007, 2015). "The findings of our present study in RGS9/R9AP-associated retinopathy are in direct contrast, providing evidence that cones are present in normal numbers but are dysfunctional." (PMID 26343007, 2015). "Adaptive-optics scanning light ophthalmoscopy will be valuable to assess whether RGS9/R9AP-associated retinopathy is indeed an entirely stationary condition, given our findings in the RGS9 subject and the increasing evidence of progression in the cone dysfunction syndromes." (PMID 26343007, 2015). "Dark-adapted red flash ERGs aid diagnosis of rod- and S-cone monochromacy, cone dystrophy, vitamin A deficiency, RDH5-retinopathy, SAG- or GRK1-retinopathy, some cases of rod-cone dystrophy, RGS9- and R9AP-retinopathy and colour vision deficiencies." (PMID 34045684, 2021). "Patients with either RGS9/R9AP-retinopathy or OT have very similar clinical phenotypes, characterised by stationary cone dysfunction, mild photophobia, normal colour vision and normal fundi." (PMID 25770143, 2016).
cancer (2 papers, 2016 to 2022). A tumor composed of atypical neoplastic, often pleomorphic cells that invade other tissues. "FAM159B co-localised with RGS9, D2R, SSTR4, and SSTR5 in the four cancer cell lines to a different extent." (PMID 36362289, 2022). "For the RGS9-DIAPH2 pair, neither of them has been reported to correlate with cancer." (PMID 27470995, 2016).
mental illness (1 paper, 2011). "The RGS9 gene is located on chromosome region 17q21-25, and the region was implicated in major mental illness susceptibility through linkage studies." (PMID 21886588, 2011).
nervous system disease (1 paper, 2021). "The mRNAs of Rgs9, Gpr88, Drd2, Sh3rf2, Tac1, Serpina 9, Rxrg, Drd1, Rasgrp2, Six3, Gpr6, Pdyn, Gng7, and Pde1b were all upregulated (p < 0.05); all of these have been reported to be more or less related to nervous system diseases." (PMID 33819195, 2021). "As the offspring became older (16 months of age), we found that some genes of benefit to nervous system disease were activated, such as Lhx8, GPR88, RGS9, CD4, DRD2, RXRG, and Syt6, following the increase in the number of cholinergic and GABAergic neurons." (PMID 33819195, 2021). "In the present study, we found that some genes of benefit to nervous system disease were activated (such as Lhx8, GPR88, RGS9, CD4, DRD2, RXRG, and Syt6), following the increase in the number of cholinergic and GABAergic neurons in the HSHF-diet offspring." (PMID 33819195, 2021). "When the offspring grew older (16 months), we found that some genes of benefit against nervous system disease were activated, such as Lhx8, GPR88, RGS9, CD4, DRD2, RXRG, and Syt6, and the expression of cholinergic and GABAergic neurons biomarker protein increased." (PMID 33819195, 2021).
RGS9 also shares sentences with these, for which no sentence is quoted: Anxiety (1 paper); cocaine addiction (1); cone-rod dystrophy (1); corneal dystrophy (1); glaucoma (1); glioma (1); Huntington disease (1); iris hypoplasia (1); lung carcinoma (1); methamphetamine dependence (1); movement disorder (1); osteoporosis (1); Photophobia (1); psychosis (1); retinitis pigmentosa (1); retinoblastoma (1); Sotos syndrome (1); substance abuse (1); Waardenburg syndrome (1).